IGKC (immunoglobulin kappa constant)
Diseases named in the same sentence as IGKC in open-access papers (continued):
Sharing a sentence is not in itself a finding about the gene and the disease.
tumor (continued). "The aim of this study was to examine the immunohistochemical (IHC) expression and clinical correlates of IGKC, CD20 and CD138 protein expression in tumours from 154 EOC cases from two pooled, prospective, population-based cohorts." (PMID 27048364, 2016). "The cell type-specific markers we used for cell annotation were as follows: T cell (CD3D); NK cell (KLRD1 and NKG7); plasma cell (IGKC and JCHAIN); Mast cell (KIT and TPSB2); tumour cell (CA9, NDUFA4L2 and SLC17A3); endothelium (PECAM1, PTPRB and KDR); mesangial cell (ACTA2 and PDGFRB)." (PMID 40830065, 2025). "Interestingly, both MNDA+ macrophages and IGKC+ macrophages were enriched in adjacent normal samples, whereas SPP1+ Macs were increased in almost all tumor samples." (PMID 39726047, 2024). "However, the expressions of IGKC, IGLC1, ITGB2, CTSS, HLA‐DPB1, and RSAD2 were elevated in tumor tissue and they served as protective factors." (PMID 37543714, 2023). "Increased staining and expression of IGKC revealed by immunohistochemistry and immunoblotting in tumor adjacent non-neoplastic lung tissues (Wilcoxon signed-rank test, p < 0.001) and in BAL cell lysates (p < 0.01) of NSCLC, respectively, were noted." (PMID 29483918, 2018). "Interestingly, genes such as TFF3, MGP, and IGKC were identified across all BL responder tumor cells, irrespective of metastatic site or tissue-specific signatures." (PMID 39955556, 2025). "We then analyzed and marked the top 20 DEG genes in tumor core regions and found that IGHG1, IGHG3, IGHG4, IGKC, and IGLC2 (effector markers for humoral immunity) were notably downregulated in core regions, possibly indicating an immunosuppressive microenvironment (ISME)." (PMID 35673582, 2022). "The level of IT+AS, but not total, ICCs positive for IGKC, a plasma cell marker, in the high HER2‐AAb group was also significantly greater than those in the low HER2‐AAb group, suggesting that tumor‐infiltrating B cells and plasma cells were involved in the production of HER2‐AAb." (PMID 33506656, 2021).
cancer (18 papers, 2012 to 2025). A tumor composed of atypical neoplastic, often pleomorphic cells that invade other tissues. "OS showed a borderline significant association with IGKC expression in Kaplan Meier analysis in ER positive carcinomas (Log-rank test: P = 0.050)." (PMID 23028600, 2012). "Notably, the gene set in the IGKC+ PT subpopulation that changed significantly with pseudotime was significantly enriched in the immune checkpoint-associated signaling pathway, suggesting that the IGKC+ PT subpopulation, similar to cancer-associated fibroblasts, might induce T-cell exhaustion." (PMID 41055342, 2025). "Previous studies have shown that non-B-cell-expressed IGKC not only functions as a natural antibody but also promotes cell proliferation, cancer development, and metastasis, in contrast to B-cell-expressed IGKC." (PMID 41055342, 2025). "Cancer‐associated genes (VIM, IGHG1‐4, IGKC, IGHA1) were upregulated, and CPCAT data revealed correlations of IREB2 with IGHG1 and VIM, and CD27 with IGHG1." (PMID 41377765, 2025). "Among the hub genes, IGKC represents an immunoglobulin, and extensive research has highlighted its impact on cancer development and immune-related factors when expressed at high levels." (PMID 37710308, 2023). "In summary, the stromal immunoglobulin kappa chain (IGKC) has been validated as an immunologic biomarker of prognosis and response to therapy in human BC and other cancers." (PMID 35205837, 2022). "IGKC expression was found to be significantly correlated with a lower T stage and improved survival and was reported as a strong immune marker in human cancer, predictive of favorable treatment response." (PMID 39409902, 2024). "In contrast, IGKC was significantly associated with DFS (Log-rank test: P = 0.009) and showed a borderline association with OS (Log-rank test: P = 0.057) in luminal B carcinomas." (PMID 23028600, 2012). "CCL15 was also increased as the pseudo-time progressed and was dominant in the end stages of the pseudo-time axis; Conversely, other key molecules such as IGHG1, IGHG3, IGHG4, IGKC, IGLC2 decreased gradually among all the carcinoma sectors in HCC1 and HCC4." (PMID 35673582, 2022). "Triple-negative cancers showed the highest expression of IGKC (median 35.76; interquartile range [IQR] 33.89–37.52) followed by HER2-positive tumors (median 35.07; IQR 33.73–36.82) and luminal cancers (median 34.29; IQR 33.05–35.58)." (PMID 34298839, 2021). "The deregulated proteins found in the pools of cancer vs. control serum samples—PEDF, IGKC, CD44, and CST3—have been previously reported." (PMID 33224883, 2020). "Similar findings were observed in node-negative breast cancer that the overexpression of IGKC was significantly associated with DFS, especially in ER negative and in luminal B carcinomas." (PMID 38874510, 2024). "In ER negative carcinomas (n = 64), both DFS and OS were significantly associated with IGKC expression." (PMID 23028600, 2012). "In the ER negative cancers, however, a higher proportion of highly proliferative cancer cells might result in a strong immune response as reflected by a strong IGKC positive infiltrate, and thus these ER negative cancers had a better survival." (PMID 23028600, 2012).
adenocarcinoma (1 paper, 2020). A common cancer characterized by the presence of malignant glandular cells. "They reported that IGKC protein expression was independently associated with longer survival, with particular impact in the adenocarcinoma cases in their cohort of NSCLC patients." (PMID 32523798, 2020).
bacterial infections (1 paper, 2025). "Notably, clinical studies have shown that patients with impaired IGKC synthesis are highly susceptible to bacterial infections, highlighting the potential advantage for pathogens in targeting or sequestering this molecule." (PMID 40570050, 2025).
neurological disorders (1 paper, 2025). "Elevated levels of IGHG3 and IGKC, components of IgG molecules, suggest ongoing humoral immune responses in the CNS, aiding in the distinction of MS from other neurological disorders." (PMID 40649948, 2025).
psychiatric disorder (1 paper, 2018). A disorder characterized by behavioral and/or psychological abnormalities, often accompanied by physical symptoms. "All these proteins except IGKC, imply the expression changes in other psychiatric disorders." (PMID 30719248, 2018).
IGKC also shares sentences with these, for which no sentence is quoted: primary Sjögren syndrome (2 papers); B-cell chronic lymphocytic leukaemia (1); benign breast tumors (1); bladder cancer (1); blood cancer (1); cardiac ischemia (1); cardiac sarcomas (1); clear cell renal cell carcinoma (1); dementia (1); diffuse systemic sclerosis (1); esophageal tumors (1); gastric tumors (1); glaucoma (1); HIV-1 infection (1); infection (1); non-Hodgkin lymphoma (1); Obesity (1); polycystic kidney disease (1); polycythemia vera (1); rheumatoid arthritis (1); sarcoma (1); viral infections (1).